CD70 (CD70 molecule)
Diseases named in the same sentence as CD70 in open-access papers (continued):
Sharing a sentence is not in itself a finding about the gene and the disease.
tumor (continued). "CD70 protein, whether expressed on dendritic cells, B cells, tumour cells, or introduced as soluble protein, promotes the survival and expansion of antigen-primed CD8+ T cells in the mouse, through dose-dependent stimulation of CD27 activity." (PMID 16892042, 2006). "Our studies showed a high-level expression of CD70 on RCC cells that might be expected to induce a strong immune response against the tumour." (PMID 16892042, 2006). "These combination strategies, involving CD70‐targeted therapies with chemotherapy, targeted agents, ICIs and other adjunctive approaches, have shown promise in remodelling the immunosuppressive tumour microenvironment and enhancing tumour‐specific immune responses." (PMID 40629902, 2025). "The role of CD70 in stromal signaling represents a previously unrecognized mechanism in skin carcinogenesis, although previous studies have shown that CAFs form a distinct stromal subset that promotes tumor cell migration, drives regulatory T cell accumulation, and correlates with poor survival." (PMID 41510255, 2025). "The mechanistic basis favoring on-tumor cytotoxicity is unknown, but it may arise due to differences in the density of CD70 antigen expression, the nature of the targeted epitope recognized, or as a secondary consequence affiliated with apparent cis-masking of CD70." (PMID 40519930, 2025). "Notably, CD70 expression did not correlate with immune cell densities within either the stroma or tumor nests, whereas high CD27 expression was associated with reduced CD45 + and CD8 + cell densities in the stroma." (PMID 40205178, 2025). "Because CD70 expression is correlated with Treg mitochondrial wellness and intracellular lipid content, impaired CD70 expression decreases Treg adaptability to the TME, leading to loss of their effector cell‐immunosuppression support of the tumour‐escaping environment." (PMID 38468489, 2024). "After tumor mutation profile and copy number variation (CNV) analyses, we established and validated a prediction model of KRAS mutations, based on survival analysis and mRNA expression, that contained seven genes: CSTF2, FAF2, KIF20B, AKR1A1, APOM, KRT6C, and CD70." (PMID 38268915, 2023). "We rationalized that increased CD70 expression in RMC could be explained by the presence of CD70+ epithelial-like cells or an increase in tumor infiltrating B cells, since CD70 was identified as a top-scoring differentially expressed gene for both clusters in our scRNA-seq analysis." (PMID 35837094, 2022). "However, CD70 dysregulation and overexpression has been observed in several cancers, where it may play a role in tumor progression and immunosuppression." (PMID 36726355, 2022). "Importantly, CD70 overexpression in MCL patients was recently reported to be associated with higher proliferation, a more aggressive clinical course of the disease, and with an increased number of Tregs infiltration in the tumor." (PMID 35681499, 2022). "CD70 might affect tumor progression directly, or indirectly by influencing the immune response." (PMID 35236310, 2022). "However, activation of the CD27/CD70 axis may also lead to tumor immunosuppressive effects by enhancing the survival of natural Tregs and inducing the apoptosis of effector T cells." (PMID 35647204, 2022). "Another study showed that overexpression of HDAC5 is related to upregulated CD70, which induces the growth suppression and apoptosis of tumor cells, indicating that targeting HDAC5 may regulate the immune response and affect tumor progression in cancer immunotherapy." (PMID 35585975, 2022). "CD204+ macrophages were the second most abundant tumor infiltrating immune cell, and when comparing to normal oral mucosa, two differently expressed genes linked to tumor associated macrophages and myeloid derived suppressor cells (MDSC) were identified: CXCL2, CD70." (PMID 36698398, 2022). "However, GBM cells may express CD70, promoting immunosuppression through tumour-induced T-cells apoptosis and Tregs’ activation." (PMID 33804731, 2021).
tumor (continued). "However, aberrant CD70 expression has been noted in tumor tissue of 25% of PDAC patients." (PMID 34439292, 2021). "Therefore, direct targeting of CD70+ tumor cells might further inhibit Treg accumulation and activation in NPC." (PMID 34568077, 2021). "Likewise, we detected the expression of CD70 and B7-H3 among various tumor cell lines." (PMID 32685008, 2020). "Immunogenic cell death induces tumor-associated antigen release and translocation of calreticulin to the tumor cell membrane, which acts as an “eat me” signal to DCs, ultimately activating intratumoral DCs that upregulate the costimulatory molecules CD86 and CD70." (PMID 32355277, 2020). "As we demonstrate high expression levels of CD70/CD27 in other tumour types using our uniform IHC method, these results underline the potential of anti-CD70 immunotherapy not only in AML, but also in other haematological malignancies and solid tumour types where CD70 is overexpressed." (PMID 31652572, 2019). "Finally, due to the expression patterns of CD70, this study might also pave the way for improved treatment options in other tumor types." (PMID 29088768, 2017). "However the presence of CD27+ TILs did not appear to be associated with CD70 expression in the tumor cells." (PMID 25951351, 2015). "However, to our knowledge, a significant association of CD70 expression on tumor cells with patient survival has not been described in these human tumors." (PMID 25792975, 2015). "Hence, during a persistent tumor-immune cell interaction, CD70 expression on tumor cells may support tumor escape from immunosurveillance and thus be disadvantageous for patient outcome." (PMID 25792975, 2015). "Functional inhibition of CD70/CD27 signaling, achieved either by generating CD70-knockout primary MM cells or with blocking monoclonal antibodies, completely abrogated tumor growth in xenotransplantation models." (PMID 41872502, 2026). "Key genes such as CD276, CD70, and CD274, known for their roles in immune modulation and tumor microenvironment influence, were notably divergent." (PMID 40299331, 2025). "CD70‐targeted immuno‐PET/CT is an emerging approach for cancer diagnosis, with the potential to improve tumour detection, assist disease staging, and monitor therapeutic response." (PMID 40629902, 2025). "ADP-520 TRuC T cells achieved potent tumor clearance in several solid tumor models, demonstrating superior clearance to C10 TRuC T cells, particularly in ACHN tumors characterized by moderate CD70 expression." (PMID 40519930, 2025). "AlloCAR70-NKT cells exhibited robust cytotoxic activity and multimodal tumor-targeting across a diverse panel of established RCC cell lines and primary patient-derived RCC tumor cells with heterogeneous CD70 expression, both in vitro and in vivo." (PMID 40885188, 2025). "Specifically, IL-17 signaling has been shown to regulate the expression of CD70 and CD80 in antigen-presenting cells while promoting TIGIT-mediated suppression in the tumor microenvironment, depending on cytokine context." (PMID 40565233, 2025). "Together with the upregulation of the stimulatory immune checkpoint molecules TNFRSF9 and CD70, which occurred after the tumour cells were treated with Pt-Au NPs and exposure to NIR, a higher fraction of apoptotic and necrotic tumour cells occurred." (PMID 40004038, 2025). "Our findings demonstrated that CD70 and CD27 are expressed in tumor cells and within the TME of SCLC, with distinct expression patterns." (PMID 40205178, 2025). "TRuC T cells were titrated by E:T against luciferase-expressing tumor cell lines, THP1, ACHN and 786-O, exhibiting a range of CD70 expression levels." (PMID 40519930, 2025). "The combination of oHSV-1 and CD70 CAR-T provides mutual enhancement of both therapies—enhancing CAR-T infiltration, activation, and survival, and “reprogramming” the tumor microenvironment from immunosuppressive to proinflammatory." (PMID 41294877, 2025).
tumor (continued). "In hematological malignancies, tumor cells co-expressing CD27 and CD70 evade immune surveillance within the tumor microenvironment, thereby promoting disease progression." (PMID 40896423, 2025). "To provide more evidence for our conclusions, we constructed anti-CD70 CAR-T cells following our previous studies to validate the ability of AZD1208 to reverse hypoxia-induced damage and enhance CAR-T cell anti-tumor function." (PMID 41199316, 2025). "CD70 was also expressed by the majority of CD68 + TAMs in both the stroma and tumor compartments, while CD3 + T-cells showed limited CD70 expression." (PMID 40205178, 2025). "For instance, in patient MC3, the predominant tumor subclone (SHM2) in the relapsed tumors showed high expression of CD70, which indicates potential responsiveness to CD70-targeted therapies." (PMID 40876452, 2025). "We found that sodium citrate-pretreated anti-CD70 CAR-T cells exhibited reduced exhaustion, increased memory T cell proportions, and enhanced anti-tumor efficacy both in vitro and in vivo." (PMID 40165944, 2025). "Both CD70 CAR-TOAd−GFP and CD70 CAR-TTS−2021 intratumoral injections strongly inhibited tumor growth and preserved mouse body weight compared to CD70 CAR-T-cell injections." (PMID 40474210, 2025). "However, in one case of papillary RCC with lung and retroperitoneal metastases, [68Ga]Ga‐NOTA‐RCCB6 showed no uptake in metastatic lesions, while 18F‐FDG PET/CT yielded positive signals, suggesting that current CD70‐targeted tracers may have limited sensitivity in tumours with low CD70 expression." (PMID 40629902, 2025). "Nanobody‐based CAR‐T cells can function as an antitumor agent in tumor microenvironment and tumor xenograft models, such as CD19 CAR‐T, CD70 CAR‐T, CD72 CAR‐T, CD105 CAR‐T, which are engineered by CRISPR/Cas9 and in silico techniques." (PMID 40536197, 2025). "CD70 and CD27 exhibit abnormal expression in various hematological and solid malignancies, contributing to tumor progression and immunosuppression within the TME." (PMID 40675157, 2025). "Optimizing CAR-T design, enhancing tumor infiltration, and modulating the TME are critical to realizing CD70’s therapeutic potential." (PMID 40896423, 2025). "In recent years, Chimeric Antigen Receptor (CAR) T-cell therapy has revolutionized hematologic cancer treatment by genetically modifying T cells to target tumor-specific antigens like CD19, CD70, BCMA, EGFR, and HER2, leading to high remission rates." (PMID 40312353, 2025). "Our study revealed a correlation between MMP14 expression and various molecules regulating tumor immune cells, including CSF1R, HAVCR2, KDR, PDCD1LG2, TGFB1, CD70, CD86, and CXCL1." (PMID 40352589, 2025). "Another anti-CD70 antibody, SGN-70, has shown potent anti-MM effects in vitro, and significantly prolongs the survival of tumor-bearing mice by lysing CD70-expressing malignant cells through Fc-dependent mechanisms." (PMID 40597436, 2025). "On the other hand, CD70-CAR-IL-15 NK cells induced a significant decrease in tumor burden compared to MOCK NK cells and a trend compared to conventional CD70-CAR NK cells over time (*significant on days 20, 21 and 22 post-treatment)." (PMID 38331849, 2024). "CD70 engages with CD27 on T cells, initiating a signaling axis that promotes cell survival, boosts T-cell proliferation, and is believed to exert anti-tumor effects." (PMID 39057061, 2024). "Together, these results provide a strong rationale to translate CD70-CAR-IL-15 NK cells to the clinic to improve outcomes for CRC and PDAC patients and potentially other tumor types that are characterized by a strong desmoplastic reaction." (PMID 38331849, 2024). "created a novel CD70-targeted tracer, [18F]RCCB6, highlighting the utility of immuno-PET/CT for assessing tumor burden and monitoring treatment responses in patients with advanced ccRCC." (PMID 39542699, 2024).
tumor (continued). "In our current study, we have developed an innovative approach utilizing nanobody-based CD70 CAR-T cells, demonstrating remarkable anti-tumor activities both in vitro and in vivo." (PMID 38637886, 2024). "With regard to other tumor types, CRC and PDAC patients displayed a median CD70 expression when evaluating CD70 expression pan-cancer on RNA-seq data available through the TCGA database." (PMID 38331849, 2024). "In summary, we have successfully developed a CD70-targeting allogeneic CAR-T cell therapy, termed SAP UCAR-T, which demonstrated enhanced in vivo persistence and tumor-eliminating ability, along with minimal safety concerns in preclinical evaluations." (PMID 39906740, 2024). "Individual positive regulatory co-stimulatory molecules (CD70, CD83, CD86) were mainly upregulated in the irradiated tumor of hRT/lena-treated mice." (PMID 38646638, 2024). "Considering that in many tumors, the CD70 protein is also overexpressed by the tumor cells themselves, we further studied the effect of POSTN on the CD70 level in GSCs." (PMID 39227950, 2024). "Monitoring the tumor immune microenvironment (TIME) is vital as CD27, the receptor for CD70, is found on relevant GB TIME cell populations ​, suggesting the potential of co-targeting GB and its microenvironment for improved therapeutic outcomes." (PMID 39328617, 2024). "CD70 contributes to the recruitment and maintenance of the immunosuppressive microenvironment in GBM, concurrently facilitating pathways that promote tumor growth, it emerges as a promising immunotherapeutic target for recurrent GBM." (PMID 39434883, 2024). "The presence of CD70 in GB but not in normal tissues supports its suitability as a therapeutic target, with CD70-directed CAR-T cells displaying significant cytotoxicity and decreased tumor growth in preclinical models." (PMID 39328617, 2024). "The CD70 and TNFSF9 genes, which are suspected tumor suppressor genes, belong to the tumor necrosis factor superfamily." (PMID 39057061, 2024). "In conclusion, we demonstrated that CD70 in CRC and PDAC patients has great therapeutic potential to target both tumor cells and tumor-promoting CAFs." (PMID 38331849, 2024). "In contrast, CD70 is aberrantly expressed on malignant cells and facilitates immune evasion through the TME and tumor progression." (PMID 37093350, 2023). "IMM40H has a dual mechanism of action: inducing cytotoxicity against CD70+ tumor cells via various effector functions (ADCC, ADCP and CDC) and obstructs the proliferation and activation of Tregs by inhibiting CD70/CD27 signaling." (PMID 37849799, 2023). "In this context, CD-70 CAR T-cells and B7H3-CAR T-cells have been investigated for GB treatment, with encouraging tumor regression results." (PMID 37020537, 2023). "In vitro pharmacology studies showed that IMM40H can induce tumor cell lysis through ADCC, ADCP, and CDC in malignant cells expressing CD70." (PMID 37849799, 2023). "All but one (ARG1) of the proteins with significantly lower expression at baseline in the p16+ tumour group also showed lower expression at 12 months—that is, PTN, TNFRSF12A, CD28, and CD70." (PMID 36835246, 2023). "For the tumor therapy applications, we also used physiological antigens (e.g., CD19, CD70) incorporated into CAR-T adoptive therapies, and the results were similar in nature to what we observed with the OVA-dependent models." (PMID 37788104, 2023). "Mice receiving SA CAR-T cells displayed slower tumor growth for a longer duration as compared with mice receiving WT CAR-T cells and TSC2–/– CD70 CAR-T cells." (PMID 37788104, 2023). "In agreement with [68Ga]Ga-NOTA-anti-CD70 VHH autoradiographs, CD70 immunoreactivity was modest in CD70low tumors and was only present at the rim of the tumor." (PMID 37093350, 2023). "Although these findings suggest that CD70 has tumor suppressor capability, it has also been implied to play an oncogenic role based on the inferior prognosis of patients with DLBCL, exhibiting high CD70 expression." (PMID 36765793, 2023).
tumor (continued). "As we demonstrated that CD70-KO and inhibition in NPC cells enhanced anti-tumor immunity by limiting Treg activities, we further investigated how CD70-CD27 signaling influenced downstream homeostasis of Tregs, particularly in the TME of NPC." (PMID 37024479, 2023). "Pre-clinical findings showed that IMM40H has a higher binding ability, stronger ability to block the interaction of CD70/CD27, and stronger ability to kill tumor cells than other CD70 competitors." (PMID 37849799, 2023). "CD70-mediated Treg immunosuppression also hampered the inflammatory response of CD8+ cytotoxic T cells, thus lowering their anti-tumor effect." (PMID 37024479, 2023). "Further, the expression of CD70 of 330 RCC specimens has been studied, and the mean expression was almost doubled in tumor samples compared to normal tissues." (PMID 38139136, 2023). "A significant level of CD70 can be detected in various types of tumor tissues and CD27 is expressed on Treg cells, but CD70 expression is low in normal tissues." (PMID 37849799, 2023). "Further, we also analyzed the immune stimulatory immune checkpoint molecules CD70, CD137-L, ICOS-L and OX40-L on the tumor cell surface." (PMID 37857049, 2023). "Consistent with the in vitro results, CD70-KO did not alter the in vivo tumorigenicity of NPC in immunodeficient NSG mice, but led to significant tumor shrink in humanized NSG mice, further confirming an inhibitory role of CD70 on anti-tumor immunity." (PMID 37024479, 2023). "We then focused on three genes (CD70, CXCL11, and HGF) which negatively correlated with favorable outcomes to further validate the key factor involved in tumor immune infiltration, especially the correlation with macrophages was mainly focused on." (PMID 35568859, 2022). "Taken together, the tumour antigens MSLN, CD70, EGFR and HER2 are being exploited as targets for target‐selective CD47 blockade for solid cancer with preclinical proof‐of‐concept for enhanced selectivity and activity." (PMID 35908284, 2022). "Blocking CD70/CD27 axis can abolish immune escape by T cell apoptosis, T cell exhaustion and Treg survival, therefore inhibiting tumor proliferation." (PMID 36588677, 2022). "Here, after a comprehensive genomic characterisation of the tumour samples from DLBCL patients in two populations, we observed a strikingly high frequency (24.0%) of gene aberrations in CD70 in the Chinese cohort." (PMID 36471481, 2022). "Constitutive expression of CD70 in a transgenic mouse model has shown that the CD27–CD70 interaction can enhance the expansion and activity of antigen‐specific CD8+ T cells and protect these mice from otherwise lethal tumours." (PMID 36471481, 2022). "To further explore the relevance of CD70 expression in RMC, we performed IHC staining on primary RMC tumor tissue sections from Patient 1 and four other RMC patients previously treated at MSKCC." (PMID 35837094, 2022). "The expression of CCL20, CD70, PCDH7, DCBLD2, and MMP14 genes were remarkably more elevated within LUAD samples than adjacent non-tumorous tissues, where PIK3R5, RNF144B, BTG2, CD69, and MEP1A genes were the opposite." (PMID 36497225, 2022). "In this review, we present the proliferative role of 15 immune checkpoints, including PD1, PD-L1, FGL1, CD155, CD47, SIRPα, CD276, IDO1, SIGLEC-15, TIM3, Galectin-9, CD70, CD27, 4-1BBL, and HVEM, in tumor progression." (PMID 36358792, 2022). "Several ligands were specifically upregulated in the tumor cell population when compared to adjacent kidney, including SPP1 and CD70." (PMID 36180422, 2022). "Previous in vitro studies have demonstrated that blocking CD70+ leukemia and B cell lymphoma cell lines using ARGX-110 can inhibit the activation of Treg and facilitate the anti-tumor immunity exerted by CD8+ effector T cells." (PMID 34568077, 2021).